IL6 (interleukin 6)
Diseases named in the same sentence as IL6 in open-access papers (continued):
Sharing a sentence is not in itself a finding about the gene and the disease.
melanoma (continued). "They demonstrated that CAF-derived conditioned medium promotes melanoma cell migration and invasion and that the simultaneous blocking of IL-6 and IL-8 with neutralising antibodies is sufficient to fully suppress CAF-induced human melanoma cell invasiveness." (PMID 34067929, 2021). "Here, we link NLRP3 activity in melanoma cells to the IL-1β induced-IL‐6/STAT3 axis, thus providing an additional mechanism to target STAT3 signaling in melanoma." (PMID 34531850, 2021). "These are EGFR, ERRFI1, IL6, JAK2, PLXNC1, RGL3 which were found to be upregulated and CBL, CDC42, PIK3R3, STAT3, UBE2D2 and YWHAZ which were found to be downregulated; Melanoma has PLXNC1 as upregulated and TGFA as downregulated gene." (PMID 34764329, 2021). "Recently, the correlation between the baseline IL-6 and CRP in melanoma treated with immune checkpoint inhibitors (ICIs) or chemotherapy was demonstrated, and higher levels of IL-6 were significantly associated with poor survival." (PMID 33531609, 2021). "The interplay between melanoma and stromal cells in the TME, including DCs, is mainly supported by presence of IL-6, IL-10, and VEGF." (PMID 33467521, 2021). "A number of studies have shown IL-6 and its major effector STAT3 as pro-tumorigenic mediators in many cancers, including melanoma, breast, lung, colon, prostate, ovarian, and hematological cancers, and to be associated with OB–OC coupling via notch signaling." (PMID 34124067, 2021). "Using a mouse model of melanoma, we report here that NLRP3 activation induces IL‐1β-mediated IL‐6 production resulting in STAT3 activation." (PMID 34531850, 2021). "In fact, MAFs secrete soluble mediators (such as pro-inflammatory proteins, MMPs, IL-6, HGF, etc.)leading to melanoma growth and progression." (PMID 34440462, 2021). "In particular, IL1A mainly stimulates the expression of proinflammatory cytokines, including IL6 and IL8 in colon cancer and melanoma." (PMID 34203721, 2021). "IL-6, TNF-α, and IFN-γ expression in melanoma cells are also suppressed by axitinib, a selective inhibitor of VEGFRs and PDGFRs." (PMID 34122447, 2021). "CD40 expression on melanoma cells stimulates the formation of CD8 T cell cytokines including IL-13, IL-6, TNF-α, and granulocyte/macrophage colony-stimulating factor (GM-CSF) and impedes brain metastasis which is common among melanoma patients." (PMID 32902664, 2021). "The overexpression of IRE1α or XBP1s enhances IL-6 expression, thereby activating the JAK/STAT3 pathway and promoting melanoma cell proliferation." (PMID 34356855, 2021). "Inhibition of BRAF/MEK signaling by silencer (si)RNA and pharmacological inhibition decreased the production of pro-tumorigenic factors such as IL-1α/β, IL-6, IL-8, IL-10, and VEGF by melanoma cells." (PMID 34576054, 2021). "Cancer cells release large amounts of cytokines including TNF-α, IL-6, IL-12, VEGF, and TNFR2, which enhances MMP-2 enzymatic activity and leads to increased invasiveness of melanoma." (PMID 34068679, 2021). "Together, these data suggest that the IER2-dependent SASP in B16 melanoma cells includes OPN, CXCL15, CCL5, IL-6, and IL-23a." (PMID 34611309, 2021). "IL-6 was known to activate STAT3 and consequently increase MMP-2 expression and the metastatic ability of cancer cells in malignant melanoma." (PMID 34267603, 2021). "Using the mouse melanoma cell line B16F10.9, which are usually resistant to TNF-α-mediated cell death, apoptosis was enhanced in the presence of IL6/sIL6R." (PMID 34411141, 2021). "Conversely, melanoma cells obtained from advanced VGP and distant metastatic lesions were shown to be completely resistant to IL-6-mediated growth inhibition." (PMID 34067929, 2021). "The levels of IL-6, IL-8, IL-10, IL-17A, IL-27, IL-31, GM-CSF, IFN-α, IL-9, VEGF-D, TNF-β, NGFβ, IL-23, IL-22, and IL-1α were below the threshold of detection in both melanoma patients and healthy controls." (PMID 33574842, 2021).
melanoma (continued). "LAG-3+ pDCs possess high potentials in producing IL-6, which suppresses the immune system via STAT3 signaling and leads to melanoma metastasis." (PMID 32902664, 2021). "Hypoxia, one of the main hallmarks of the melanoma microenvironment, enables dermal fibroblasts to enhance the secretion of VEGF-A, stromal-derived factor-1 (SDF-1) and IL-6, which cooperate to promote melanoma cell chemotaxis and invasion." (PMID 34067929, 2021). "Specifically, it was found that elevated S100B in malignant melanoma cells blocks CREB phosphorylation and inhibits IL6/STAT3-signaling." (PMID 34411141, 2021). "Serum expression of IL-1b, IL-6, IP-10, PDGF-BB, and RANTES was found to be significantly different in melanoma vs. controls, reinforced by a much larger patient cohort, since previous observations were carried out on much smaller patient cohorts." (PMID 33302400, 2020). "The acquisition of an HIF1/NFkB-directed proinflammatory phenotype was characterized by the induced production and release of several factors, including TNFα, CCL5, IL6, VEGFA, CXCL8, PGE2 and CCL2, which had a prosurvival effect on melanoma cells." (PMID 32967672, 2020). "In humans, there is a positive feedback loop between IL-6 and WNT5A in melanoma cells, and WNT5A-FZD4/LRP5 signalling supports self-renewal of embryonic stem cells and eMSCs." (PMID 32552749, 2020). "Single-molecule analysis of serum expression identified IL-1b, IL-6, IP-10, PDGF-BB, and RANTES differently expressed in melanoma (p < 0.05)." (PMID 33302400, 2020). "IL‐6 and TGF‐β have been identified as the primary activators of MAF on CD8+ T cells, contributing to the suppression of melanoma microenvironment." (PMID 32931642, 2020). "Hundreds of factors can be secreted by adipocytes, and we focused on TNF-α and IL-6, which have been reported to regulate PD-L1 on kinds of cancer cells but HCC or melanoma." (PMID 32477009, 2020). "Accordingly, the clinical translatability of specific IL-6 and CXCL12 inhibitors has been evaluated in preclinical models of melanoma and colorectal carcinoma." (PMID 32967079, 2020). "It was recently shown that adipocytes secret IL6, which leads to downregulation of MIR211 in melanoma which further promotes melanoma invasion." (PMID 33628737, 2020). "Adding recombinant IL-6 to melanoma cells reversed those in vitro and in vivo effects, suggesting that ATF3 expression by HDFs regulates melanoma progression through the IL-6/STAT3 pathway." (PMID 32373541, 2020). "The tumor microenvironment of melanoma is shaped by the level of MITF expression and depletion of MITF stimulates the release of inflammatory cytokines such as IL-6 and IL-1β." (PMID 33293474, 2020). "Nevertheless, two patients in our study demonstrated an immediate and parallel decrease of IL-6 and S100B serum levels after administration of checkpoint inhibitor treatment which might result from a direct suppressive effect of PD-1 blockade on melanoma cell cycle." (PMID 32188047, 2020). "To investigate the importance of this signalling molecule, we next blocked IL‐6 and WNT5A signalling as well as Cdc42‐GTPase activation itself in BRAFi‐R melanoma cells and studied how these treatments affected the cellular actin network." (PMID 30582770, 2019). "We used a highly sensitive WST‐1 cell proliferation assay to assess the antiproliferative effect of BRAFi treatment following direct inhibition of IL‐6 and WNT5A signalling in HTB63‐R and A375‐R BRAFi‐R melanoma cell lines." (PMID 30582770, 2019). "Consistent with the findings of elevated IL‐6 secretion and WNT5A expression, we observed increased migration and invasion of these BRAFi‐R melanoma cells compared with their parental HTB63, A375 and A2058 cells." (PMID 30582770, 2019). "Subsequently, it was experimentally shown that the regulation of melanoma angiogenesis by KAI1 occurred through the inhibition of blood vessel formation in matrigel plugs, along with the down-regulation of IL-6 and VEGF." (PMID 30643005, 2019).
melanoma (continued). "Concomitant incubation with sEVs that had been isolated from the A375 cell line, or patient-derived melanoma cells DMBC12 and DMBC21, increased the secretion of IL-12, as well as IL-6, while the levels of VEGF were slightly reduced." (PMID 31269655, 2019). "In human melanoma cells, BRAFV600E was shown to drive the expression of interleukin 6 (IL-6), IL-10 and vascular endothelial growth factor (VEGF), cytokines that, in vitro, promote a tolerogenic monocyte-derived dendritic cell (DC) phenotype." (PMID 31762942, 2019). "To investigate the importance of IL‐6 and WNT5A signalling for the increased invasive migration of BRAFi‐R melanoma cells, we separately or in combination blocked these signalling molecules." (PMID 30582770, 2019). "Based on our present observations, we conclude that simultaneous inhibition of IL‐6 and WNT5A signalling effectively obstruct Cdc42‐dependent migration and invasion of BRAFi‐R melanoma cells." (PMID 30582770, 2019). "To evaluate the independent and combined effects of IL‐6 and WNT5A signalling on the invasive migration of BRAFi‐R melanoma cells, we first blocked WNT5A or IL‐6 signalling separately in HTB63‐R and A375‐R cells by using either Box5 or an IL‐6 Ab." (PMID 30582770, 2019). "In detail, melanoma cells which overexpress STAT3 protein inhibit the expression of proinflammatory cytokines and chemokines, such as VEGF, IL-10, and IL-6." (PMID 31569642, 2019). "Based on these observations, we analyzed the ratio between the levels of IL-10 and the other cytokines (IL-6 and CXCL1) in the melanoma microenvironment." (PMID 31374840, 2019). "PTX significantly augmented IL-6 and IL-8 expressions in MDA-MB-231 BCA and in MDA-MB-435 melanoma cells whereas XIAP mRNA was also induced by PTX but was not statistically significant." (PMID 29486738, 2018). "A lot of researchers have reported about the imbalance of cytokines in patients with melanoma - statistically low levels of IL-2 and IFN-γ and high levels of IL-4, IL-6 and IL-10 that reflects the imbalance between Th1/Th2 immune responses." (PMID 29849947, 2018). "Different cytokines, like IL-6, TNF-α, IFN-γ, IL-10, and TGF-β1, have been reported to play a role in the progression and immunosurveillance escape of melanoma." (PMID 30149677, 2018). "Our group demonstrated that IL-6, a TLR signaling product, can activate STAT3 with resulting overexpression of Wnt5a in human papillary thyroid carcinoma, melanoma and pancreatic cancer." (PMID 29371911, 2017). "Several cytokines, including GDF15, IL-6, IL-8, IL-18 and MIA, have been identified by shotgun MS in a study of secretomes of lung metastases derived from melanoma and breast cancer." (PMID 29236046, 2017). "Compared with normal melanocytes, six melanoma cell lines showed higher XBP1 splicing and enhanced IL-6 expression." (PMID 28222747, 2017). "Differentiation of IL-10-producing regulatory DC has also been shown to be driven by autocrine IL-6/IL-10 signaling through STAT3 in DC, which is initiated by melanoma-derived factors that activate the TLR2 signaling pathway in these cells." (PMID 29209327, 2017). "Our results suggested that in melanoma cells, the constitutive activation of STAT3 is activated by secreted extracellular IL-6 working in an autocrine/paracrine manner, which can be abolished by adding IL-6 antibodies to the medium, thus neutralizing IL-6." (PMID 28222747, 2017). "Here, we demonstrated that XBP1s activated IL-6 expression by binding to its promoter in human melanoma cells, thus indicating the conservation of XBP1 behavior in controlling IL-6 expression." (PMID 28222747, 2017). "The three melanoma cell lines (WM852, HTB63 and A375) studied expressed different levels of WNT5A protein and secreted different amounts of IL-6." (PMID 27191257, 2016). "In three invasive melanoma cell lines, endogenous WNT5A protein expression was related to IL-6 protein secretion." (PMID 27191257, 2016).
melanoma (continued). "In line with that, MEDICA suppressed the IL-6- and HGF-activated phospho-STAT3(Tyr705) in CRC HT29 or PTC BcPAP cells, and the constitutively-active STAT3 in A375 melanoma cells." (PMID 26959890, 2016). "WNT-5A induces the release of IL-6, MMP2, and vascular endothelial growth factor (VEGF) containing exosomes from melanoma cells in a Ca2+- and CDC42-dependent process that requires cytoskeletal reorganization." (PMID 26514730, 2016). "CCL2 has been shown to regulate expression of IL-6 expression in lung fibroblasts and VEGF in melanoma cells." (PMID 27283985, 2016). "Taking a more feasible therapeutic approach, we treated two different melanoma cell lines (WM852 and HTB63) with Box5 (100 μM) and/or a neutralising anti-IL-6 antibody (1 μg/ml) and checked their migration/invasion." (PMID 27191257, 2016). "Next, we confirmed these findings by qRT–PCR for the TNF-α responsive genes IL1B and IL6 using independent MITF siRNAs in MZ7 and two other MITFhigh melanoma cell lines, Ma-Mel-15 (MM15) and Ma-Mel-27 (MM27), respectively." (PMID 26530832, 2015). "As IL-1β and IL-6 are bona fide TNF-α targets, this delineates a potent feed-forward mechanism of melanoma dedifferentiation instigated by TNF-α." (PMID 26530832, 2015). "We also observed that IL-6 and VEGF-A are able to enhance the expression of β3-AR in melanoma cells, while β2-AR is upregulated by IL-8, FGF-2 and VEGF-A, thereby suggesting a feed-forward loop between NE and its cognate receptors β3/β2-ARs." (PMID 25474135, 2015). "Recently, it was established that IL-6, a pro-inflammatory cytokine, can up-regulate the expression of WNT5A in melanoma cells, in a p38α-MAPK dependent manner." (PMID 26393652, 2015). "Furthermore, c-Jun engagement by TNF-α and other cytokines such as IL-1β and IL-6 is critical to trigger inflammation-induced dedifferentiation of melanoma cells and the progressive acquisition of a pro-inflammatory cell state that characterizes MITFlow/c-Junhigh melanoma cell lines and tumours." (PMID 26530832, 2015). "The presence of an inflammatory response in the B16 melanomas treated with LTX-315 was further indicated by increased mRNA levels of inflammatory cytokines such as interleukin (IL) 1β, IL6 and IL18 in the tumor tissue and of IL6 in plasma samples." (PMID 24676901, 2014). "We previously reported an interorgan system in which stress-related hormones (corticosterone and noradrenaline), interleukin-6, and glutathione (GSH) coordinately regulate metastatic growth of highly aggressive B16-F10 melanoma cells." (PMID 24802641, 2014). "We show that WNT5A signaling induces a Ca2+-dependent release of exosomes containing the immunomodulatory and pro-angiogenic proteins IL-6, VEGF and MMP2 in melanoma cells." (PMID 24766647, 2014). "Here we show that, in melanoma cells with low endogenous WNT5A expression, the stimulation with rWNT5A induces a rapid release of exosomes containing the immunomodulatory cytokine IL-6 and the pro-angiogenic factors IL-8, VEGF and MMP2." (PMID 24766647, 2014). "Our results confirm our previous observations in metastatic B16 melanoma-bearing mice that treatment with RU-486, a GCR blocker, induces a decrease in circulating IL-6." (PMID 24802641, 2014). "We then further tested the levels of IL-6 and IL-8 by ELISA in four melanoma cell lines (Hs294T, SK-Mel-2, SK-Mel-5 and SK-Mel-28) treated with MLN8237 or vehicle and confirmed that both IL-6 and IL-8 were increased following MLN8237 treatment." (PMID 23180582, 2013). "Thus, there are various mechanisms by which melanoma cells may escape inhibition by OSM or IL-6." (PMID 24381786, 2013). "Significantly, SOID-8 inhibits IL-6-induced STAT3 and JAK2 activation in melanoma cells, further supporting this notion." (PMID 23166634, 2012).
melanoma (continued). "Serum cytokine levels (including IL-1α, IL-1β, IL-2, IL-6, IL-10, IL-12, TNF-α, IFN-γ and IFN-α) were lower in A375 melanoma bearing mice treated with G3139 + VRP + ACV + PAC.PBP + DNR + X rays than in controls treated with physiological saline." (PMID 22233801, 2012). "Human, melanoma cell-derived cytokines elevated by DMXAA included GM-CSF, IL-6, IP-10, MCP-1, GRO and IL-8." (PMID 22415295, 2012). "We lastly investigated the IL-6 production from CTL co-cultured with immature DC and both melanoma cells treated with chemotherapeutic agents and H-1PV." (PMID 22029859, 2011). "Key chemokines and cytokines, such as IL-1 beta, IL-8, IL-6 and CCL2/MCP1, were significantly upregulated in fibroblasts co-cultured with the invasive melanoma lines (BLM and MV3) compared to fibroblasts co-cultured with noninvasive (WM164) cells." (PMID 24212647, 2011). "The high incidence of expression of TGF-β, IL-8, IL-6, VEGF, PDGF-AA, OPN, IGF-1 and IL-15 by human melanoma supports consideration of these factors in future planning of therapy." (PMID 24281094, 2010). "Melanoma cells release a number of osteoclastogenic factors including TGF-β, IL-6, M-CSF, GM-CSF and TNF-α; these cells also upregulate osteoblast expression of factors known to stimulate RANKL-dependent osteoclastogenesis." (PMID 16641914, 2006). "In vivo, CRP reflects Il-6 secretion supported by high correlation between serum CRP and Il-6 concentrations in melanoma patients." (PMID 15280926, 2004). "Twelve patients undergoing IL-2 and flavone acetic acid (FAA) combination immunotherapy for advanced melanoma were studied throughout treatment for the induction of measurable levels of bioactive TNF, GM-CSF and IL-6 in their serum." (PMID 8512819, 1993). "In addition, we investigated several tumor progression proteins that are frequently assessed in the clinical evaluation of melanoma, such as LDH, S100, IL-6, and TNF-α." (PMID 40564098, 2025). "IL-6 and TNF-α enhance the survival and proliferation of melanoma cells." (PMID 40636453, 2025). "We next tested whether OA exposure impacts systemic IL-6 and found higher IL-6 levels in the peripheral blood of C57BL/6 animals injected with melanoma cells from aged-MFP-melanomas." (PMID 40280124, 2025). "Additionally, melanoma-derived EVs enriched with HSP72 and HSP105 activate TLR2 and TLR4 on DCs to promote IL-6 production." (PMID 40908470, 2025). "IL-6 secreted by MAFs induces the invasiveness of melanoma cells; however, the exact mechanism has not been elucidated." (PMID 40136652, 2025). "Although increased STAT3 and NF-κB activity in IκBζ-expressing melanoma could explain the elevated expression of IL-6 and IL-1 cytokines, STAT3 and NF-κB inhibition was unable to recover IκBζ-mediated suppression of Cxcl9, Cxcl10, and Ccl5 in melanoma cells." (PMID 40562773, 2025). "This suggests that CCNB1-driven IL-6 secretion may stimulate NK cells to release pro-invasive signals such as TGF-β, which in turn promotes melanoma invasiveness." (PMID 40430484, 2025). "Like IL6/STAT3, genetic and pharmacological targeting of GLI1 showed that IFNγ/STAT1 requires functional GLI as a second signal for the full-blown induction of IDO1 in human melanoma cells." (PMID 39962447, 2025). "Moreover, their inhibition led to a reduction in key pro-inflammatory cyto-chemokines genes, such as CCL2, IL6, and CXCL8, regulated by NFkB-mediated transcription and contributing to melanoma cell survival and to immunosuppressive TME." (PMID 41550951, 2025). "Cytokines and growth factors secreted by CSCs shape the behavior of fibroblasts and surrounding immune cells (TGF-β, IL-6, IL-8), while signals emitted by the stroma (CAF-derived factors or immune cells) can maintain or even pronounce the melanoma stem phenotype." (PMID 40806546, 2025). "However, melanoma cells within the TME secrete IL-6, IL-10, VEGF, and TGF-β, which disrupt DC recruitment and maturation, thereby impairing T-cell activation and promoting melanoma progression." (PMID 40936894, 2025).